RHOJ (ras homolog family member J)
Diseases named in the same sentence as RHOJ in open-access papers (continued):
Sharing a sentence is not in itself a finding about the gene and the disease.
gastric cancer (2 papers, 2023 to 2024). A primary or metastatic malignant neoplasm involving the stomach. "RHOJ, a member of RHO guanosine triphosphatases family, is observed to be overexpressed in EMT‐subtype gastric cancer with decreased CDH1 expression and high mesenchymal genes expression." (PMID 39092293, 2024). "Recent research suggests that RHOJ can activate the IL‐6/ signal transducer and activator of transcription 3 signaling, resulting in EMT‐induced invasion and metastasis of gastric cancer." (PMID 39092293, 2024).
bladder cancer (1 paper, 2023). "We discovered an association between elevated RHOJ expression in bladder cancer patients and inferior prognosis with decreased survival rates, indicating its potential value as a prognostic indicator." (PMID 37762382, 2023). "Considering the increasing emphasis on immunotherapeutic strategies in bladder cancer management, our findings on RHOJ’s potential as a diagnostic biomarker and its association with immune response open new avenues for therapeutic interventions." (PMID 37762382, 2023). "This highlights a poorer prognosis and significantly lower survival rates in bladder cancer patients with elevated RHOJ expression." (PMID 37762382, 2023). "To investigate possible links between RHOJ gene expression and cancer cell metastasis in individuals with bladder cancer, we utilized the MEXPRESS tool to analyze clinical data obtained from the TCGA BLCA database." (PMID 37762382, 2023). "Our findings underscore the need for further research on RHOJ to fully appreciate its potential in improving the diagnosis, prognosis, and treatment of bladder cancer." (PMID 37762382, 2023). "In this study, we aimed to assess the expression of RHOJ in bladder cancer and its implications for prognosis in patients treated with BCG." (PMID 37762382, 2023). "This positions RHOJ as a potential biomarker for assessing the prognosis of BCG-treated bladder cancer patients." (PMID 37762382, 2023). "The bladder cancer patients were stratified into two groups based on their RHOJ expression levels: high expression and low expression." (PMID 37762382, 2023). "This study investigates the function and consequences of RHOJ, a member of the Rho GTPase family, in patients with bladder cancer." (PMID 37762382, 2023). "Furthermore, the analysis of gene sets for enrichment provided interesting insights into the potential functional effects of RHOJ expression in bladder cancer." (PMID 37762382, 2023). "With the recent advances in immune checkpoint inhibitors for the treatment of bladder cancer, comprehending the role of RHOJ in immune modulation could yield valuable insights for optimizing immunotherapy strategies." (PMID 37762382, 2023). "In summary, our investigation comprehensively examined the implications of RHOJ in bladder cancer." (PMID 37762382, 2023). "Notably, our results suggest that RHOJ could have a notable influence on bladder cancer, particularly regarding disease progression and survival rates." (PMID 37762382, 2023).
brain glioma (1 paper, 2022). A malignant glioma that involves the brain. "RhoJ level increased with a higher grade of human brain gliomas by IHC analysis." (PMID 35173528, 2022).
cutaneous melanoma (1 paper, 2017). A primary melanoma arising from atypical melanocytes in the skin. "Although RhoJ is highly expressed in the heart and to a lesser extent in the liver, its expression in cutaneous melanoma has not been extensively analyzed." (PMID 28753606, 2017).
endometriosis (1 paper, 2020). The growth of functional endometrial tissue in anatomic sites outside the uterine body. "It is, thus, possible to assume that the RHOJ gene can be involved in the development of endometriosis." (PMID 33153202, 2020). "A relationship was observed in those studies between the rs10129516 polymorphism, located on chromosome 14 at the intergene—PARP1P2 and RHOJ—area, and endometriosis." (PMID 33153202, 2020).
glioma (1 paper, 2022). A benign or malignant brain and spinal cord tumor that arises from glial cells (astrocytes, oligodendrocytes, ependymal cells). "We analyzed the expression of RhoJ in different grade gliomas and investigated its role in GBM angiogenesis in vivo and in vitro." (PMID 35173528, 2022). "In this study, we firstly verified that the expression of RhoJ was positively correlated with the malignancy of glioma." (PMID 35173528, 2022).
nevus (1 paper, 2017). Nevus (or naevus, plural nevi or naevi, from nævus, Latin for "birthmark") is the medical term for sharply circumscribed[1] and chronic lesions of the skin or mucosa. "RhoJ played an even more important role during the process of nevus formation and most significantly affected tumor development and metastasis." (PMID 28753606, 2017). "In this study, we utilize physiologically-relevant in vivo systems to examine the role that RhoJ and its downstream targets PAK-BAD play in nevus formation and cellular transformation." (PMID 28753606, 2017). "RhoJ deletion in BRAF mutant melanocytes modulates the expression of the pro-apoptotic protein BAD as well as genes involved in cellular metabolism, impairing nevus formation, cellular transformation, and metastasis." (PMID 28753606, 2017).
Obesity (1 paper, 2024). Accumulation of substantial excess body fat. "Interestingly, in our model, and as was expected, RhoJ expression was upregulated in the HME1 cells exposed to the obesity micro-environment (4-fold change) compared to HME1 cells at both the mRNA and protein levels." (PMID 38247865, 2024).
pancreatic cancer (1 paper, 2020). "A total of 26 genes were found to be significantly associated with poor prognosis, while five of them, including SYT12, GJB5, RHOJ, GJB3 and IFI27, were of particular interest as they have not been previously associated with poor outcomes in pancreatic cancer cases." (PMID 32724299, 2020).
postmenopausal osteoporosis (1 paper, 2020). Metabolic disorder associated with fractures of the femoral neck, vertebrae, and distal forearm. "Clinical evidence shows that the methylation state of CpG sites of zinc finger protein 267 (ZNF267), actin binding LIM protein family member 2 (ABLIM2), Ras homolog family member J (RHOJ), and cyclin dependent kinase like 5 (CDKL5) genes is correlated with postmenopausal osteoporosis." (PMID 32664681, 2020).
triple-negative breast carcinoma (1 paper, 2023). An invasive breast carcinoma which is negative for expression of estrogen receptor (ER), progesterone receptor (PR), and human epidermal growth factor receptor 2 (HER2).
Urothelial/Bladder Carcinoma (1 paper, 2023). "We analyzed the relationship between RHOJ expression and prognosis in patients with urothelial tumors using the TCGA BLCA (The Cancer Genome Atlas Urothelial/Bladder Carcinoma), GSE31684, and GSE32894 databases." (PMID 37762382, 2023).
uveal melanoma (1 paper, 2023). A melanoma derived from melanocytes of the uveal tract. "To identify possible regulators of the Gαq/PDZ-RhoGEF/RhoJ pathway we conducted an in silico analysis through data mining of the TCGA uveal melanoma study, which includes transcriptomic and clinical data from 80 patients." (PMID 37958718, 2023). "Although our current results are consistent with the potential oncogenic role of the Gαq-Q209L/PDZ-RhoGEF/RhoJ axis, we should keep in mind that this emerging possibility warrants future investigations in preclinical models of uveal melanoma." (PMID 37958718, 2023). "Expressions of GNAQ, ARHGEF11, RHOJ and the fourteen selected signaling partners, analyzed in TCGA uveal melanoma patients and uveal melanoma cell line datasets, revealed parallelism, with GNAQ, ARHGEF11, and RHOJ being among the highest expressed transcripts in both groups." (PMID 37958718, 2023). "Using relational data mining of uveal melanoma patient TCGA datasets, we got an insight into the signaling landscape that accompanies the Gαq/PDZ-RhoGEF/RhoJ axis." (PMID 37958718, 2023).
vascular skin disease (1 paper, 2025). "RhoJ-targeting drugs have a particular proclivity for blocking skin vascularization, nominating them as new treatments for inflammatory/vascular skin disease." (PMID 40950721, 2025).
tumor (28 papers, 2014 to 2026). "RHOJ promotes the function of tumor-associated endothelial cells and drives EMT through its interaction with the IPO9/EpCAM signaling pathway, thereby increasing cell survival and drug resistance." (PMID 41548474, 2026). "In tumor models, endothelial RhoJ deficiency suppressed angiogenesis and exacerbated vascular permeability, which was partly ascribable to the enhancement of the RhoA-ROCK signal." (PMID 33916163, 2021). "The effect of RhoJ deficiency was stronger in tumour settings, where it drastically decreased tumour angiogenesis and growth." (PMID 33573141, 2021). "Silencing RHOJ inhibited M2 tumor-associated macrophage activation." (PMID 41548474, 2026). "Gene enrichment analysis revealed high RHOJ expression in tumor-associated endothelial cells." (PMID 41548474, 2026). "RHOJ regulates epithelial-to-mesenchymal-transition-associated resistance to chemotherapy by enhancing the response to replicative stress and activating the DNA damage response, enabling tumour cells to rapidly repair DNA lesions induced by chemotherapy." (PMID 36949199, 2023). "Finally, we investigated the association between RHOJ expression and the tumor immune microenvironment in urothelial tumors." (PMID 37762382, 2023). "Moreover, the high expression of RHOJ demonstrated a significant correlation with diverse clinical features linked to cancer metastasis and disease advancement, highlighting its worth as a crucial biomarker for disease severity and tumor aggression." (PMID 37762382, 2023). "RHOJ controls drug resistance by enhancing replicative stress response, activates DNA damage response and enables tumour cells to rapidly repair DNA lesions induced by chemotherapy." (PMID 40442778, 2025). "Taken together, this work identifies small molecules that target RhoJ as selective tumor anti-vascular agents." (PMID 40950721, 2025). "Our data suggests RhoJ as a potential novel molecular driver of tumor development in breast tissues and a mediator of cell resistance to conventional chemotherapy through PAK1 activation." (PMID 38247865, 2024). "Our data demonstrate that RHOJ promotes resistance to therapy in EMT tumour cells by modulating DNA repair and activating dormant replication origins through the regulation of formin-dependent nuclear actin polymerization." (PMID 36949199, 2023). "We found that RHOJ, a small Rho GTPase, is overexpressed in tumour cells presenting EMT compared with in epithelial tumour cells." (PMID 36949199, 2023). "Overall, researchers concluded the major function of RHOJ in promoting chemoresistance of EMT tumor cells based on the short-term and long-term chemotherapy studies in vivo." (PMID 37779170, 2023). "To understand how RHOJ regulates DNA repair and the activation of origins of DNA replication after chemotherapy, we sought to identify the proteins that interact with RHOJ in EMT tumour cells." (PMID 36949199, 2023). "RHOJ overexpression in EPCAM+ tumour cells strongly decreased the proportion of apoptotic tumour cells 24 h after cisplatin/5FU administration and leads to increased cell survival 48 h after chemotherapy." (PMID 36949199, 2023). "Using in vitro genetic gain- or loss-of-function studies, they found that overexpression of RHOJ lead to increased tumor cell survival following chemotherapy, whereas knockdown of RHOJ sensitized tumor cells to chemotherapy." (PMID 37779170, 2023). "Taken together, these findings indicate that RHOJ can facilitate GC cells' proliferation and tumor growth as well." (PMID 37781036, 2023). "Ras Homolog Family Member J (RhoJ) is expressed in endothelial cells and promotes endothelial cell migration and tumor angiogenesis." (PMID 37626776, 2023). "Our analysis indicates that RHOJ expression levels significantly impact survival rates, tumor progression, and immune response in urothelial tumors." (PMID 37762382, 2023).
tumor (continued). "RHOJ controls several aspects of tumorigenesis, including tumour initiation and tumour growth, by regulating the rate of tumour cell proliferation." (PMID 36949199, 2023). "We found, through genetic gain and loss of function studies in vitro and in vivo, the key role of RHOJ in regulating the resistance of EMT tumour cells to chemotherapy." (PMID 36949199, 2023). "High RHOJ expression correlated with poor prognosis, advanced disease stages, and an increase in monocyte population within the tumor microenvironment." (PMID 37762382, 2023). "All these data demonstrated that RHOJ promotes chemotherapy resistance in EMT tumor cells by activating DNA-damage response and enhancing DNA replication via the regulation of nuclear actin polymerization." (PMID 37779170, 2023). "Immunostaining of HA-tagged-RHOJ-expressing tumour cells showed the cytoplasmic, perinuclear and nuclear localization of RHOJ." (PMID 36949199, 2023). "Whereas small GTPases of the Rho family have been previously associated with DNA repair and response to therapy, the role of RHOJ in regulating resistance to therapy in EMT tumour cells was unclear." (PMID 36949199, 2023). "The variation in RHOJ expression across different immune cell populations indicates its potential impact on the tumor immune microenvironment, highlighting its significance in cancer immunotherapy." (PMID 37762382, 2023). "The overexpression of RHOJ in EPCAM+ tumour cells slightly decreased the growth of cells in vitro and did not affect the expression of EMT or epithelial markers." (PMID 36949199, 2023). "Rhoj KO slightly decreased the number of tumours per mouse and increased their latency, suggesting that RHOJ promotes SCC initiation." (PMID 36949199, 2023). "RHOJ interacts with proteins that regulate nuclear actin, and inhibition of actin polymerization sensitizes EMT tumour cells to chemotherapy-induced cell death in a RHOJ-dependent manner." (PMID 36949199, 2023). "Using genetic gain and loss of function studies, we identified RHOJ, a small Rho GTPase, as a key regulator that promotes resistance to a broad range of chemotherapeutic agents in EMT tumour cells." (PMID 36949199, 2023). "From this analysis, a clear link between RHOJ gene expression and lympho-vascular invasion, tumor stage, metastasis stage, lymph node invasion, and pathological stage emerged." (PMID 37762382, 2023). "Based on the findings RHOJ is upregulated notably in EMT-subtype GC and associated with patients' poor survival, after RHOJ overexpression observed that RHOJ contributes to GC cells' EMT, migration, invasion, tumor growth, and metastasis." (PMID 37781036, 2023). "CDC42 family GTPases (RHOJ, RHOQ, CDC42) are upregulated but rarely mutated in cancer and control both the ability of tumor cells to invade surrounding tissues and the ability of endothelial cells to vascularize tumors." (PMID 35385746, 2022). "CDC42 family GTPases (RHOJ, RHOQ, CDC42) are linked to multiple human cancers and modulate cell-cycle progression, tumor cell migration/invasion, and tumor angiogenesis." (PMID 35385746, 2022). "New structure-based, protein-protein interaction targeting strategies are needed to develop selective drug-like inhibitors that target all members of the CDC42 family, particularly given the important role of RHOJ in tumor angiogenesis." (PMID 35385746, 2022). "Recent studies have revealed that RhoJ blockade destroys tumor blood vessels by activating the RhoA- ROCK signaling pathway in various tumor models." (PMID 35173528, 2022). "Both IHC and IF staining results showed that the expression of CD31, RhoJ, EpCAM, and moesin were significantly increased in tumor tissues derived from the RhoJ-overexpressing group." (PMID 35173528, 2022).